ANG (angiogenin)
Diseases named in the same sentence as ANG in open-access papers (continued):
Sharing a sentence is not in itself a finding about the gene and the disease.
metastatic disease (3 papers, 2015 to 2023). "Proteins upregulated in serum of patients with metastatic disease included C-reactive protein and IC1 (SERPING1), factors involved in immunity and inflammation, and angiogenin, protein involved in angiogenesis." (PMID 26376850, 2015).
oral cancer (3 papers, 2020 to 2023). "Thus, we propose that one needs to be cautious when using serum ANG levels as a potential marker for oral cancer." (PMID 32471132, 2020). "We further identified ANG, a previously known tumor promotor that mediates TGFBR3-dependent suppression of migration and invasion of oral cancer cells." (PMID 32471132, 2020). "We demonstrated that TGFBR3 induces the abundance of secreted angiogenin (ANG), a known pro-angiogenic factor, and ANG is essential and sufficient to mediate TGFBR3-dependent inhibition of migration and invasion of oral cancer cells." (PMID 32471132, 2020).
anaplastic thyroid cancer (2 papers, 2020). "Apatinib was reported to suppress angiogenesis in anaplastic thyroid carcinoma by blocking the Akt/GSK3/ANG pathway; however, the effect of apatinib in PTC is unclear." (PMID 32219060, 2020).
brain cancer (2 papers, 2019 to 2024). A primary or metastatic malignant neoplasm affecting the brain. "Currently, some ANG‐drug conjugates are already in clinical trials for brain cancers, demonstrating the potential of the ANG‐LRP1 interaction in brain targeted therapies." (PMID 39276062, 2024). "Angiogenin (ANG), an endogenous protein that plays a key role in cell growth and survival, has been scrutinised here as promising nanomedicine tool for the modulation of pro-/anti-angiogenic processes in brain cancer therapy." (PMID 31500197, 2019). "Indeed, since ANG plays a key role in cell growth and survival, and the role of VEGF in brain tumour angiogenesis has been demonstrated, new perspectives in the therapeutic approaches may rely on the tiny modulation of the pro-/anti-angiogenic processes for brain cancer treatment." (PMID 31500197, 2019).
brain tumors (2 papers, 2019 to 2024). "Taking into account the correlations between angiogenin protein and copper in physiological and pathological conditions of the brain, a promising pharmacological approach in brain tumours therapy is the use of ANG as molecular target, whose activity may be modulated by the presence of copper ions." (PMID 31500197, 2019).
fibrosis (2 papers, 2015 to 2024). the formation of excess fibrous connective tissue in an organ or tissue in a reparative or reactive process. "During CHC treatment, patients with SLD had distinct cytokine and growth factor kinetics, with SLD being the main source of variation in several cytokines (IL-5, IL-9, IL-10, IL-13, IL-17A, IL-22) and growth factors (EGF, VEGF and ANG), and it seems this was independent of fibrosis stage." (PMID 39200991, 2024).
infarct (2 papers, 2012 to 2018). "In our study, angiogenin levels measured before IRT were not correlated with infarct size, probably because those measures were performed after the most acute phase of the disease." (PMID 30008694, 2018).
motor neuron degeneration (2 papers, 2015). "In addition, various syndromes of motor neuron degeneration are caused by mutations in other genes such as Progranulin/GRN, Angiogenin/ANG, CHMP2B, Spastin/SPAST, PRPH, VAPB, and Alsin/ALS2." (PMID 25955410, 2015).
osteoporosis (2 papers, 2021 to 2025). A condition of reduced bone mass, with decreased cortical thickness and a decrease in the number and size of the trabeculae of cancellous bone (but normal chemical composition), resulting in increased fracture incidence. "It is reasonable that future studies consider agents/approaches that activate the ANG‒ribosome biogenesis pathway as a therapeutic schema for pediatric osteoporosis or osteonecrosis, especially for patients receiving long-term GC treatment." (PMID 33758201, 2021). "We therefore conducted a case–control study of youth with DMD on chronic GCs with and without osteoporosis to determine if there was an association between factors isolated from serum (PDGF-BB, VEGF, and angiogenin) and PBMC subpopulations (POCs, SPCs, and CD34+) cells) with subsequent fractures." (PMID 40080633, 2025).
proliferative diabetic retinopathy (2 papers, 2011 to 2019). Advanced retinopathy due to diabetes mellitus characterized by the formation of new vessels in the retina. "Angiogenin, FGF-basic and PlGF levels were previously shown to be elevated in the vitreous of proliferative diabetic retinopathy patients, CNV membranes from patients with AMD and/or mouse models of laser-induced CNV." (PMID 31731799, 2019). "Although the role of angiogenin in neovascular eye diseases has not been established, its concentration in the vitreous of proliferative diabetic retinopathy patients has been shown to be elevated." (PMID 21364907, 2011).
respiratory failure (2 papers, 2020 to 2024). The significant impairment of gas exchange within the lungs resulting in hypoxia, hypercarbia, or both, to the extent that organ tissue perfusion is severely compromised. "Compared with ALS patients without ANG mutations, patients with mutations were more critically ill, and most of them were diagnosed with medulla oblongata ALS and died of respiratory failure within 2 years of onset." (PMID 38421827, 2024).
tuberculosis (2 papers, 2020 to 2025). A chronic, recurrent infection caused by the bacterium Mycobacterium tuberculosis. "Taken together, we define Angiogenin as a novel endogenous AMP and derive the small, bioactive fragment Angie1, which is ready to be tested for therapeutic activity in animal models of tuberculosis and infections with fast-growing bacterial pathogens." (PMID 33537017, 2020).
arteriosclerosis (1 paper, 2013). A vascular disorder characterized by thickening and hardening of the walls of the arteries. "BMSC noticeably increase Angiogenin expression in the arterial wall and ischemic brain which correlate with arteriosclerosis-like changes." (PMID 24303036, 2013). "However, BMSC treatment in T1DM rats significantly increased vascular inflammatory response identified by increased Angiogenin, MMP9 and ED1 expression as well as increased arteriosclerosis-like vascular structure changes." (PMID 24303036, 2013).
chronic liver failure (1 paper, 2025). Liver failure that develops slowly and gradually for some time, possibly for years, often as the result of cirrhosis, or malnutrition. "Recently we have demonstrated that in an acute-on-chronic liver failure model, C/EBPβ activation was mediated by endothelial ANG signaling." (PMID 40288442, 2025).
chronic obstructive lung disease (1 paper, 2012). "Moreover serum angiogenin concentrations were not in correlation with any of the clinical variables as for example: CRP, WBC, tumour size, stage of the disease, chronic obstructive lung disease (COPD), etc." (PMID 23412843, 2012).
chronic viral hepatitis (1 paper, 2024). "Further studies showed that 5’tRHs levels may be closely related to the expression of ANG, and the differences in the localization and function of ANG in cells may lead to changes in 5’tRHs levels in chronic viral hepatitis and HCC." (PMID 38622694, 2024).
clear cell renal cell carcinoma (1 paper, 2023). "This study provides novel biological insights into molecular mechanisms of ccRCC, and suggests angiogenin and its receptors as potential therapeutic targets in clear cell renal cancer." (PMID 38025776, 2023).
cutaneous T cell lymphoma (1 paper, 2024). "Increased HMGB1 secretion also correlates with cutaneous T cell lymphoma condition (CTCL), corresponding to increases in IL-4, IL-10, IL-19, and angiogenin." (PMID 39682695, 2024).
delirium (1 paper, 2022). A disorder characterized by confusion; inattentiveness; disorientation; illusions; hallucinations; agitation; and in some instances autonomic nervous system overactivity. "With reference to the differentially expressed proteins in proteomics and combined with the results of KEGG and GO analysis, five proteins with high expression in delirium patients were selected: MAGI-2, SAP, FGL, ANG, and AACT." (PMID 35294925, 2022).
endometritis (1 paper, 2025). An acute or chronic, usually bacterial infectious process affecting the endometrium. "Angiogenin (Ang), a secretory vertebrate-specific ribonuclease, exhibits antimicrobial activity and has been implicated in inflammation; however, its specific role in endometritis pathogenesis remains unknown." (PMID 40723465, 2025).
Granuloma (1 paper, 2019). A compact, organized collection of mature mononuclear phagocytes, which may be but is not necessarily accompanied by accessory features such as necrosis. "Immunohistochemistry demonstrated that one of these proteins, Angiogenin, specifically localized to the caseous regions of selected MAC-LD granulomas." (PMID 32010116, 2019).
invasive carcinoma (1 paper, 2004). A carcinoma that is not confined to the epithelium, and has spread to the surrounding stroma. "There was a significant positive correlation in 253 invasive carcinomas from tissue microarrays between DEC1 and tumour grade (P=0.01), HIF-1α (P=0.04) and the hypoxically regulated gene angiogenin (P<0.0001)." (PMID 15328513, 2004).
ischemic disease (1 paper, 2024). Lack of blood supply to an area of the body, resulting in impairment of tissue oxygenation. "Angiogenin is a multi-functional protein which participates in regulating the hematopoietic regeneration, vascularization and blood vessel homeostasis, thereby being one of major biomarkers for predicting vascular regenerative efficacy of MSCs in the treatment of ischemic diseases." (PMID 38853252, 2024).
kidney cancer (1 paper, 2024). Primary or metastatic malignant neoplasm involving the kidney. "This increase correlates with the increased expression of related proteins, like ANG, which also intensively contributes to kidney cancer angiogenesis." (PMID 39062015, 2024).
lactic acidosis (1 paper, 2008). Metabolic acidosis characterized by the accumulation of lactate in the body. "Genes induced by lactic acidosis included: PLAUR, ERBB3, CD55, interleukin 15, CXCL16, angiogenin and MHC class I genes." (PMID 19057672, 2008).
laryngeal squamous cell carcinoma (1 paper, 2021). A squamous cell carcinoma that arises from the larynx. "For example, a study analysed ANG expression in 108 operable laryngeal squamous cell carcinoma tissues and found ANG expression to be related to carcinoma recurrence rate and disease-free survival (DFS)." (PMID 34512316, 2021). "Previous studies have found ANG expression to be significantly high in cases with loco-regional recurrent disease in laryngeal squamous cell carcinoma; ANG expression ≥ 5.0% is considered a significant, independent, negative prognostic factor in terms of DFS." (PMID 34512316, 2021).
lung adenocarcinoma (1 paper, 2018). A carcinoma that arises from the lung and is characterized by the presence of malignant glandular epithelial cells. "Nuclear expression of angiogenin has been shown in about two thirds of lung adenocarcinomas, and target inhibition impairs xenograft tumor proliferation and angiogenesis." (PMID 30352093, 2018). "Overall, this study presents distinct transcriptomic differences between lung adenocarcinoma growth patterns, which could be validated for the solid-expressed ITPKA and the lepidic-expressed angiogenin proteins." (PMID 30352093, 2018).
lymph node metastasis (1 paper, 2017). "Several proangiogenic factors associated with interstitial hypertension-associated lymph node metastasis were identified in BxPC-3 and Capan-2 tumors, and three of these factors were up-regulated in high IFP/highly metastatic tumors in both models: TGFB, ANG, and IGF1." (PMID 28624797, 2017).
medulloblastoma (1 paper, 2016). A malignant, invasive embryonal neoplasm arising from the cerebellum. "Expression of SerpinE1/PAI-1 (*1), Angiogenin (*2) and IGFBP-3 (*3) were notably low in medulloblastoma conditioned media, but SerpinE1/PAI-1 and IGFBP-3 were in fact present in BMEN1 cells." (PMID 27255663, 2016).
meningitis (1 paper, 2015). A disorder characterized by acute inflammation of the meninges of the brain and/or spinal cord. "Such an interaction could inactivate the angiogenin inhibitor, thus promoting angiogenesis and vascular permeability that could allow S. suis to cross the blood–brain barrier and cause meningitis." (PMID 26611338, 2015).
migraine (1 paper, 2017). "This close cooperation between angiogenin and VEGF emphasizes our observation of lowered levels of both proangiogenic factors in migraine patients." (PMID 28918499, 2017).
ovarian carcinoma (1 paper, 2017). A malignant neoplasm originating from the surface ovarian epithelium. "Taken together ligation PCR and Northern analysis confirm that ANG participates in the biogenesis of tRF5-Glu in ovarian cancer cells." (PMID 29221134, 2017). "We applied similar methods to confirm that ANG is responsible for the biogenesis of tRF5-Glu in ovarian cancer cell lines." (PMID 29221134, 2017). "We performed RNAi knockdown of ANG expression in ovarian cancer cell lines to determine if ANG has a role in generating tRF5-Glu in ovarian cancer cells." (PMID 29221134, 2017).
psoriasis (1 paper, 2018). An autoimmune condition characterized by red, well-delineated plaques with silvery scales that are usually on the extensor surfaces and scalp. "Serum ANG levels were decreased in patients with psoriasis compared with those in healthy controls." (PMID 29736193, 2018).
respiratory paralysis (1 paper, 2024). Complete or severe weakness of the muscles of respiration. "Previous case reports have shown that ALS patients with ANG mutations mostly have bulbar-onset ALS, and most patients have respiratory dysfunction, ultimately dying from respiratory paralysis or pulmonary infections." (PMID 38421827, 2024).
sarcoidosis (1 paper, 2025). Sarcoidosis is a multisystemic disorder of unknown cause characterized by the formation of immune granulomas in involved organs. "We identified nine biomarkers (IL-1β, IL-6, IL-8, IL-13, VEGF, angiogenin, C4a, RANTES, and MCP-1) that significantly differ in the BAL of patients with HP and sarcoidosis and showed that RANTES and IL-6 are associated with fibrotic outcome." (PMID 40725075, 2025). "The levels of VEGF and angiogenin were significantly different in the BALF of patients with HP, sarcoidosis, amiodarone lung, and EGPA." (PMID 40725075, 2025). "Sarcoidosis patients had decreased levels of IL-1β, IL-5, IL-8, IL-12p70, TNF-α, angiogenin, C3a, C4a, RANTES, and MCP-1 and increased levels of IL-2, IL-4, IL-6, IL-13, IFN-γ, and VEGF." (PMID 40725075, 2025). "Based on our results, 9 possible biomarkers were identified (IL-1β, IL-6, IL-8, IL-13, VEGF, angiogenin, C4a, RANTES, and MCP-1) out of 18 tested that significantly differ in the BALF of patients with HP and sarcoidosis." (PMID 40725075, 2025). "On the other hand, the levels of angiogenin in the lung were higher in patients with EGPA (p = 0.001), amiodarone lung (p = 0.01), and HP (p = 0.007) and reached significance in comparison to patients with sarcoidosis, which showed the lowest level of angiogenin." (PMID 40725075, 2025).
Schnitzler syndrome (1 paper, 2018). A rare, underdiagnosed disorder in adults characterized by recurrent febrile rash, bone and/or joint pain, enlarged lymph nodes, fatigue, a monoclonal IgM component, leukocytosis and systemic inflammatory response. "In addition, serum ANG levels were significantly increased in patients receiving hemodialysis compared with those in healthy controls and patients with Schnitzler syndrome compared with those in healthy controls." (PMID 29736193, 2018).
squamous cell carcinoma (1 paper, 2016). A carcinoma arising from squamous epithelial cells. "Angiogenin-mediated rRNA transcription has been revealed to be related to squamous cell carcinoma." (PMID 27517048, 2016).
thyroid autoimmunity (1 paper, 2025). "In the subgroup with coexisting autoimmune thyroiditis, angiogenin was further increased, distinguishing this cohort and suggesting a shared pro-angiogenic and inflammatory mechanism linking diabetes and thyroid autoimmunity." (PMID 41515940, 2025).
uveal melanoma (1 paper, 2017). A melanoma derived from melanocytes of the uveal tract. "The present study, however, is the first to show upregulation of angiogenin in uveal melanoma." (PMID 27878431, 2017). "Additional studies are needed to elucidate the functional role of angiogenin, IL-8, and MCP-1 in uveal melanoma." (PMID 27878431, 2017). "Angiogenin, MCP-1, and IL-8 were significantly up-regulated in uveal melanoma compared to ARMD, similar to the results of the comparison with benign tumors." (PMID 27878431, 2017). "Large-scale studies are necessary to evaluate whether angiogenin, MCP-1, and IL-8 in the aqueous humor are specific and sensitive markers of malignant uveal melanoma." (PMID 27878431, 2017). "The results of the present study demonstrate that angiogenin, MCP-1, and IL-8 in the aqueous humor were significantly up-regulated in malignant uveal melanoma and may be potential markers for distinguishing uveal melanoma from benign pigmented intraocular tumors." (PMID 27878431, 2017).
worm infection (1 paper, 2010). "Whereas, in the resistant mice, other proteins (such as Relm-β, Tff3, and angiogenin) may be retained and effectively concentrated at the sites of worm infection." (PMID 20138044, 2010).